MFN1 (mitofusin 1)
Description:
Mitochondrial outer membrane GTPase that mediates mitochondrial clustering and fusion. Membrane clustering requires GTPase activity. It may involve a major rearrangement of the coiled coil domains. Mitochondria are highly dynamic organelles, and their morphology is determined by the equilibrium between mitochondrial fusion and fission events. Overexpression induces the formation of mitochondrial networks (in vitro). Has low GTPase activity.
Synonyms: FLJ20693; hfzo1; hfzo2
Tractability: Small molecule: a structure with a bound ligand is known. Antibody: UniProt predicts a signal peptide or a membrane-spanning region. PROTAC: UniProt records ubiquitination sites on it; ubiquitination databases record sites on it; its protein half-life has been measured.
Gene: Protein-coding gene on chromosome 3 (179,346,952 to 179,394,940, forward strand). Ensembl gene ENSG00000171109.
Subcellular location: Mitochondrion outer membrane; Cytoplasm (Isoform 2)
Subcellular location (Human Protein Atlas): Mitochondria
Pathways (Reactome):
Autophagy: PINK1-PRKN Mediated Mitophagy
Hemostasis: Factors involved in megakaryocyte development and platelet production
Signal Transduction: RHOT2 GTPase cycle
Gene Ontology:
Molecular function: GTPase activity; identical protein binding; protein binding; GTP binding
Biological process: GTP metabolic process; mitochondrial fusion; mitochondrion localization; mitochondrion organization; positive regulation of mitochondrial membrane potential
Cellular component: cytoplasm; membrane; mitochondrial outer membrane; mitochondrion; outer mitochondrial membrane protein complex
Genetic constraint (gnomAD): Loss-of-function variants: 53 observed, 69.76 expected, observed/expected ratio (o/e) 0.76, 90% interval 0.61 to 0.95. The upper end of that interval is the gene's LOEUF score, 0.95, which puts it in group 4 of 6, group 1 being the genes least tolerant of losing a copy. Missense variants: 691 observed, 769.89 expected, observed/expected ratio (o/e) 0.9, 90% interval 0.84 to 0.96. Synonymous variants: 265 observed, 269.79 expected, observed/expected ratio (o/e) 0.98, 90% interval 0.89 to 1.09.
Homologues: Orthologues: macaque MFN1 (98% identical), chimpanzee MFN1 (92% identical), rabbit MFN1 (92% identical), dog MFN1 (92% identical), pig MFN1 (91% identical), mouse Mfn1 (91% identical), rat Mfn1 (91% identical), guinea pig MFN1 (90% identical), zebrafish mfn1b (70% identical), tropical clawed frog mfn1 (68% identical), Drosophila melanogaster Marf (47% identical), zebrafish MFN1 (39% identical), and 1 more. Paralogues in human: MFN2 (63% identical).
Diseases named in the same sentence as MFN1 in open-access papers:
MFN1 is named in the same sentence as 159 diseases in open-access papers, as found by Europe PMC text mining. Sharing a sentence is not in itself a finding about the gene and the disease. The quoted sentences say what the papers report.
breast carcinoma (32 papers, 2015 to 2025). "Research has suggested that the proapoptotic effects of MLT on 4T1 breast cancer cells are associated with the upregulation of mitofusin 1 (Mfn1) and dynamin-related protein 1 (Drp1)." (PMID 38017537, 2023). "Moreover, both Drp1 deficiency and Mfn1 overexpression in breast cancer cells inhibited formation of lamellipodial formation, which is essential for metastasis." (PMID 35712666, 2022). "Moreover, breast cancer cells with low Mfn1 expression are more migratory and thus overexpression of Mfn1 is associated with mitochondrial elongation, which significantly inhibits the metastatic ability of breast cancer cells." (PMID 34868997, 2021). "In addition, we found that BRCA1 mutation increased MFN1/2 expression in breast cancer patient‐derived xenograft (PDX) models." (PMID 32195105, 2020). "In cluster 1, breast cancer cell markers, including Nob1, Vmp1, Crk, Ckap2, Parp14 and Mfn1, were detected among the top cluster markers." (PMID 39054536, 2024). "Silencing DRP1 or overexpressing Mfn1 led to mitochondrial elongation or clustering, respectively, significantly inhibiting the metastatic ability of breast cancer cells." (PMID 39179991, 2024). "The overexpression of MFN1 or silencing of Drp1 leads to mitochondrial elongation or aggregation, which in turn significantly reduces the metastasis of breast cancer cells." (PMID 37669960, 2023). "A recent study suggested that mitochondrial fusion through the miR200C-PGC1α (peroxisome proliferator activated receptor γ coactivator 1)-MFN1 pathway facilitates EMT during breast cancer progression." (PMID 33479369, 2021). "We next examined the expression of fusion- and fission-related proteins (Drp1, Mfn1, and Mfn2) in breast cancer cells." (PMID 26517089, 2015). "In an isogenic model spanning normal, transformed, and metastatic breast cancer cells, levels of Mitofusin 1 (MFN1) progressively declined while dynamin related protein 1 (DRP1) became increasingly active, correlating with fragmented mitochondria during cancer progression." (PMID 40691145, 2025). "Furthermore, Drp1 knockdown or Mfn1 overexpression induces mitochondrial elongation and significantly inhibits breast cancer cell metastasis, indicating that Drp1 can serve as a novel target for limiting breast cancer metastasis." (PMID 36192752, 2022). "Metastatic breast cancer cells were found to enhance mitochondrial fission, increased DRP1 expression, and decreased mitofusin-1 expression." (PMID 33807275, 2021). "We also found that high expression of mitofusins (Mfn1/2) correlated with poorer MFS to the bone and brain in patients with breast cancer." (PMID 32503622, 2020). "Thus, in metastatic breast cancer cells, active DRP1 in combination with low MFN1 levels tips the balance towards fission, whereas increased OPA1 levels tighten cristae and CJ." (PMID 40691145, 2025). "By contrast, DRP1 and MFN1/2 knockout decreased stem cell differentiation in mouse embryonic cortex development and human mammary epithelial cells, respectively, and OPA1 shRNA knockdown had the same effect on human breast cancer cell lines." (PMID 38156294, 2023). "Many tumors exhibit fragmented mitochondria with upregulated DRP1 and decreased expression levels of MFN1 and MFN2255 in ovarian cancer, HCC,257 lung cancer, colon cancer, breast cancer, neuroblastoma, and glioblastoma, which are correlated to the metastatic potential of cancer cells." (PMID 38156294, 2023). "Additionally, overexpression of MFN1 or MFN2 greatly reduced migratory and invasive capacity of these cells, supporting the idea that metastatic breast cancer cells drive migration and invasion through fragmentation of the mitochondria pool." (PMID 35356277, 2022). "Even though MFN1 expression levels in breast cancer also correlate with worse prognosis, our data indicate that MFN1 or MFN2 deletion does not affect breast cancer cells migration, proliferation, or adhesion." (PMID 35279198, 2022).
breast carcinoma (continued). "For example, overexpression of Drp1 was detected in breast cancer metastatic cells compared to the non-metastatic, whereas silencing of Drp1 or overexpression of Mfn1 resulted in mitochondrial elongation and significantly suppressed the metastatic properties of breast cancer cells." (PMID 31921862, 2019). "Compared with non-metastatic breast cancer cells, metastatic breast cancer cells have higher expression of DRP1 and lower expression of MFN1." (PMID 37602332, 2023). "Compared to non-metastatic breast cancer cells, metastatic cells exhibited more fragmented mitochondria, higher levels of total and active DRP1, and lower expression of mitochondrial fusion protein 1 (Mfn1)." (PMID 39179991, 2024).
heart failure (23 papers, 2012 to 2025). Inability of the heart to pump blood at an adequate rate to meet tissue metabolic requirements. "Ferreira et al68 designed a peptide named SAMβA that selectively antagonizes the association between beta II protein kinase C (βIIPKC) and Mfn1 to deactivate Mfn1, thus attenuating heart failure after MI." (PMID 34160885, 2021). "A report from Dorn’s group exhibits that hearts deficient in Mfn1 and Mfn2 contribute to progressive dilated cardiomyopathy at five weeks and heart failure from seven to eight weeks." (PMID 34026850, 2021). "Intriguingly, while MFF -/- mice died at ~13 weeks from dilated cardiomyopathy caused heart failure, when crossed with MFN1 -/- mice, which die at embryonic stage, the double MFF -/-; MFN1 -/- mice do considerably better." (PMID 33810506, 2021). "Immunoblot analysis of anti-βIIPKC immunoprecipitates with anti-Mfn1 and anti-serine/threonine antibodies demonstrated increased Mfn1-βIIPKC association and phosphorylation at the molecular size of Mfn1 in heart failure samples that were reduced by SAMβA." (PMID 30659190, 2019). "Our study provides evidence that inhibition of excessive Mfn1-βIIPKC interaction and the resulting mitochondrial fragmentation and dysfunction are critical to heart failure-associated pathophysiology." (PMID 30659190, 2019). "Analysis of anti-Mfn1 immunoprecipitates by immunoblotting with anti-βIIPKC antibody demonstrated an increased association of βIIPKC with Mfn1 in cardiac mitochondria isolated from rats with heart failure." (PMID 30659190, 2019). "The preclinical studies described here suggest that βIIPKC activation contributes to heart failure by inhibiting Mfn1, therefore causing accumulation of fragmented/dysfunctional mitochondria, most likely resulting from impaired mitochondrial fusion." (PMID 30659190, 2019). "Mfn1 phosphorylation results in partial loss of its GTPase activity and in a buildup of fragmented and dysfunctional mitochondria in heart failure." (PMID 30659190, 2019). "For example, knocking out Mfn1 and Mfn2 in mice caused lethal heart failure, as it abolished mitochondrial tethering and fusion of the outer membrane, leading to fragmented, smaller, and poorly organized mitochondria." (PMID 28044126, 2016). "Using a rationally designed peptide that selectively antagonizes Mfn1-βIIPKC association (SAMβA), we determine the contribution of Mfn1-βIIPKC interaction and the resulting phosphorylation of Mfn1 to mitochondrial morphology and bioenergetics and to the pathology associated with heart failure." (PMID 30659190, 2019). "Finally, we confirmed that Mfn1 phosphorylation and inhibition by βIIPKC alone is a major contributor to the pathophysiology associated with heart failure in this post-myocardial infarction heart failure rat model, using SAMβA, a rationally designed selective antagonist of Mfn1-βIIPKC association." (PMID 30659190, 2019). "It has been reported that cardiac deficiency of Mfn1 and Mfn2 exhibits progressive DCM and heart failure in succession." (PMID 36776252, 2023). "A study showed that MFN1/MFN2 double knockout mice died at the embryonic stage due to heart failure." (PMID 36776252, 2023). "Previous studies have observed an increase in MFN1 and alterations in its activity in MI and heart failure." (PMID 35883722, 2022). "Although Drp1 and Mfn1/2 are candidates for treating heart failure by modulating mitochondrial morphology, these molecules are critical and fundamental regulators for maintaining mitochondrial morphology and functions." (PMID 35789860, 2022). "Other reports suggest that mitochondrial fusion events via OPA1 or MFN1/2 appear to decrease in heart failure, as well." (PMID 34912235, 2021). "Although, direct modulation of Mfn1 and Mfn2 by the sex hormones is still unclear in heart failure, several studies have indicated estrogen and testosterone are cardioprotective factors." (PMID 34026850, 2021).
heart failure (continued). "Sustained inhibition of Mfn1-βIIPKC interaction using SAMβA re-established mitochondrial number to size ratio in heart failure compared to sham group." (PMID 30659190, 2019). "Here, we use the global βIIPKC inhibitor to identify mitofusin 1 (Mfn1) as a downstream βIIPKC substrate involved in heart failure progression." (PMID 30659190, 2019). "We demonstrated that during heart failure, βIIPKC translocated to the mitochondrial outer membrane, where it is bound to and phosphorylated Mfn1." (PMID 30659190, 2019). "Moreover, another rationally-designed peptide (SAMβA) that selectively antagonizes intracellular Mfn1–βIIPKC association, protects cultured neonatal and adult cardiac myocytes, and re-establishes mitochondrial morphology and function and improves cardiac contractility in rats with heart failure." (PMID 30995799, 2019). "Immunoblot analysis of anti-Mfn1 immunoprecipitates with anti-serine/threonine antibody revealed an increased phosphorylation at the molecular size of Mfn1 in heart failure samples that was reduced by inhibiting βIIPKC activity with βIIV5-3." (PMID 30659190, 2019). "The striking difference between our mosaic analyses and previous organ-wide ablation of Mfn1/2 in CMs suggests that secondary effects of heart failure confounded studies of organ-wide Mfn1/2 cardiac KO32." (PMID 30242271, 2018). "Combined Mfn1 and Mfn2 ablation in mouse hearts resulted in accumulation of dysfunctional and fragmented mitochondria and led to lethal heart failure at approximately 8 weeks after Mfn1/Mfn2 ablation." (PMID 25652199, 2015). "Furthermore, Mfn1/Mfn2 double-KO mice develop heart failure during embryonic life, leading to death." (PMID 40520935, 2025). "The same approach was also used to target mitofusin 1 (Mfn1), a GTPase homologous protein that is localized to the outer mitochondrial membrane where it mediates mitochondria fusion as a downstream PKCβII substrate involved in heart failure pathophysiology." (PMID 38139336, 2023). "Impairment of metabolism has been reported to occur with the progression of heart failure, and the findings of the present study indicate that Mfn1 may be critically involved in this detrimental process." (PMID 33762690, 2021). "QSG could also act on the expression of mitochondrial fusion/split protein, upregulate the expression of MFN1/2 and OPA1, inhibit the expression of DRP1 and FIS1, and reduce mitochondrial disorders and oxidative stress damage caused by heart failure." (PMID 35003305, 2021). "Developing methods for activation of Mfn1 and mitochondrial dynamics could lead to next generation therapy for severe heart failure." (PMID 33762690, 2021). "Our data also suggest that correcting impaired mitochondrial dynamics, in general, and selectively inhibiting Mfn1-βIIPKC interaction with drugs, such as SAMβA, may provide useful treatments for patients with established heart failure." (PMID 30659190, 2019). "Here the authors show, in a rat model of myocardial infarction, that heart failure outcome can be improved by selectively inhibiting the interaction between βIIPKC and its downstream mitochondrial target Mitofusin-1, and that this strategy is superior to global βIIPKC inhibition." (PMID 30659190, 2019). "Finally, we compared the benefit of treatments with βIIV5-3 (a global βIIPKC inhibitor) relative to SAMβA (a selective Mfn1-βIIPKC protein–protein interaction inhibitor) in improving ventricular function and remodeling in heart failure." (PMID 30659190, 2019). "Therefore, sustained blockage of Mfn1-βIIPKC interaction was critical to protect against accumulation of fragmented/dysfunctional mitochondria with an impact on cell death in heart failure." (PMID 30659190, 2019).
heart failure (continued). "In addition, Naruse et al77 found that increasing the expression of GLP‐1 in the intestine after heart failure caused by hypertension can both boost the expression of OPA1 and Mfn1, as well as accelerate the phosphorylation and deactivation of Drp1, subsequently improving mitochondrial function." (PMID 34160885, 2021). "Given that βIIPKC and Mfn1 accumulated on the outer mitochondria membrane during heart failure, and that blocking global βIIPKC activity reduced mitochondrial Mfn1 levels and re-established the mitochondrial number to size ratio, we next determined whether βIIPKC and Mfn1 form a complex." (PMID 30659190, 2019). "Only the levels of Mfn1 (a mitochondrial fusion-related enzyme) were elevated in cardiac mitochondria during heart failure, yet its GTPase activity was significantly reduced as compared to the sham group, suggesting accumulation of dysfunctional Mfn1 in heart failure." (PMID 30659190, 2019). "And this tethering may play a role in disease onset and progression; for example, Mfn-1/2 are downregulated in heart failure impairing mitochondrial fusion and SR function, which in turn lead to decreased SR calcium load and, over time, to decreased calcium release." (PMID 28044126, 2016). "The results of the current study indicate that suppression of Mfn1 expression and disruption of mitochondrial dynamics are involved in the pathology of patients with non-responsive heart failure." (PMID 33762690, 2021). "Taken together, these results suggest that the β-AR/cAMP/PKA/miR-140-5p signaling pathway down-regulates Mfn1 expression in cardiac tissues of non-responding patients with heart failure." (PMID 33762690, 2021). "βIIPKC inhibition by βIIV5-3 selectively re-established cardiac Mfn1 levels and activity in heart failure, without affecting the level or activity of mitofusin 2 (Mfn2)." (PMID 30659190, 2019). "This suggests that the elevated levels of MFN1 and MFN2 observed in the failing heart may result from impaired proteasome activity, consistent with findings from animal models of heart failure and human cardiac failure." (PMID 40520935, 2025). "However, mfn1/2 and OPA1 overexpression may improve mitochondrial functions and inhibit cardiac failure." (PMID 24675698, 2014).